CST3 (cystatin C)
Diseases named in the same sentence as CST3 in open-access papers (continued):
Sharing a sentence is not in itself a finding about the gene and the disease.
kidney damage (continued). "We show that P-cystatin C, U-A1M and P-urea are more sensitive markers of kidney damage compared to the traditional kidney injury marker P-creatinine." (PMID 32824680, 2020). "Previous research has shown that serum cystatin C was a biomarker of kidney damage and was superior to serum creatinine." (PMID 33114531, 2020). "IL-6 and cystatin-C, as markers of inflammation and kidney damage, respectively, are likely to provide insight into prediction of risk for CKD outcomes after AKI, as our feasibility data suggest that IL-6 is a more sensitive than high sensitivity-CRP." (PMID 30898807, 2019). "Persistent hyperglycemia induced nephropathy as evidenced by an increase in the kidney-to-body weight ratio, proteinuria and elevated plasma cystatin C levels in wild type mice." (PMID 27618774, 2016). "After induction of kidney damage by puromycin, there was a strong increase in cystatin C staining in the proximal tubules as well as de novo staining in additional tubular segments." (PMID 25310591, 2014). "TRAIL-/-ApoE-/- mice had significantly increased urine protein, urine protein:creatinine ratio, plasma phosphorous, and plasma cystatin C, with accelerated nephropathy." (PMID 24667560, 2014). "Albuminuria is an early detection and progression marker of nephropathy in diabetic or hypertensive patients, preceding plasma cystatin C and creatinine." (PMID 22900035, 2012). "For example, in some patients with urinary stones, larger kidney stones accompanied by significantly elevated cystatin C levels may indicate early kidney damage." (PMID 40551898, 2025). "The estimation GFR based on serum Cystatin C (eGFRcys) has been suggested to show better clinical utility for detecting nephropathy in patients with normoalbuminuria, as well as predicting the progression of nephropathy in patients with albuminuria." (PMID 39011442, 2024). "The selected biomarkers, cystatin C, KIM-1 (kidney injury molecule-1), and NGAL (neutrophil gelatinase-associated lipocalin), were evaluated in a study for their efficacy as indicators of early kidney damage in dogs with dilated cardiomyopathy." (PMID 38731309, 2024). "This suggests that cystatin C may be a particularly good marker of early kidney damage in obese children with metabolic disorders." (PMID 39409098, 2024). "Healthy mice had no development of kidney damage (Cystatin C) or associated changes in platelet activation evidenced by urinary thromboxane analysis." (PMID 37503167, 2023). "This includes KNG, an important pro-inflammatory and pro-oxidant factor belonging to the kallikrein-kinin-system that regulates cardiovascular and renal function; Cystatin-C, a recognized biomarker of kidney damage, MetS and CVD predictor; as well as the previously cited ApoB." (PMID 36829843, 2023). "In addition, these 106 potential classifiers/biomarkers between TCMR vs. STA are associated with kidney damage (e.g., ATP1B1, CST3, FAH, GSS, HPX and LYZ), tubule injury (e.g., CRYM, GSS, HAGH, HPX and LYZ) and kidney inflammation (e.g., DCN)." (PMID 36814924, 2023). "Non-DM (healthy) mice had no development of kidney damage (Cystatin C) or associated changes in platelet activation evidenced by urinary thromboxane analysis." (PMID 37975061, 2023). "Moreover, urinary microalbumin was found to be considered as markers for early detection of nephropathy with significant correlation with serum cystatin C." (PMID 35622665, 2022). "Serum cystatin C adds significance for diagnosing early kidney damage, as our study showed it could be successfully used in young patients with T1D for estimating GFR." (PMID 35208542, 2022). "Serum Cystatin-C is used to monitor renal function and detect kidney damage." (PMID 36094936, 2022). "The main finding of our study was that using cystatin C helped to find those young T1D patients who may be suffering from early kidney damage, as one-third of the whole cohort was classified with worse eGFR levels when using cystatin C vs. creatinine." (PMID 35208542, 2022).
kidney damage (continued). "Concentration of cystatin C increases with the progression of nephropathy in T2DM patients." (PMID 33996155, 2021). "Thus, serum cystatin C had higher accuracy in diagnosing nephropathy than serum creatinine in the Nepalese T2DM patients." (PMID 33996155, 2021). "Novel biomarkers for kidney function (serum cystatin C, proBNP, osteopontin) or kidney damage (NGAL, interleukins 6 and 18) have shown promise for prognostication of AKI and have been assessed in studies evaluating RRT discontinuation as well as kidney function recovery and kidney damage repair." (PMID 33099671, 2021). "However, as it was reported for the UA analysis, in HA children and adolescents with developed carious lesions, cystatin C values, already at the upper level of the normal values, should be considered an early indicator of nephropathy." (PMID 33143057, 2020). "Finally, we showed that these non-DM (healthy) mice had no development of kidney damage (Cystatin C) or associated changes in platelet activation using in vivo urinary thromboxane analysis." (PMID 37975061, 2023). "The present study provided evidence that the expression level of urinary exosomal miRNA-615-3p correlated with serum Cystatin C, so urinary exosomal miRNA-615-3p might be useful as a marker of the inflammatory response and the progression of kidney damage in DKD." (PMID 36695327, 2023). "Therefore, cystatin C is more sensitive to kidney damage than serum creatinine." (PMID 33828483, 2021). "However, since cystatin C is increased by inflammation, it has to be seen whether the pro-inflammatory status at baseline or the actual kidney damage is a better predictor OPG evolution." (PMID 22333484, 2012). "Following GEN, all rats exhibited a reduction in glomerular filtration, as seen by increased blood levels of cystatin-C, BUN, and creatinine, which are considered the most sensitive indicators for detecting kidney damage in the experimental trials." (PMID 40464943, 2025). "Plasma cystatin C levels and u-ACR in B12-treated mice were closer to sham levels, indicating preserved glomerular filtration and reduced kidney damage, along with the restoration of eGFR in both injury groups." (PMID 41300434, 2025). "In this study, the authors focused on analyzing cystatin C, KIM-1, and NGAL measured in blood serum as biomarkers of early kidney damage in dogs with stage B2 DCM." (PMID 38731309, 2024). "Promising biomarker candidates for kidney damage in Bothrops snakebites were retinol-binding protein (RBP4), beta-2-microglobulin (B2M), cystatin-C (CST3), hepcidin (HAMP), and fatty acid-binding protein (L-FABP)." (PMID 38536893, 2024). "In previous studies of kidney injury during HFRS, the levels of U-NGAL, U-A1M and P-Cystatin C were increased in patients with AKI, indicating their potential as kidney damage biomarkers." (PMID 32824680, 2020). "In clinical practice, kidney damage markers such as ACR have predominantly been used complementary with serum markers such as creatinine and cystatin C. A direct comparison between these two types was beyond the scope of this study." (PMID 28629425, 2017). "Studies have shown that serum cystatin C is more sensitive than serum creatinine and can reflect kidney function changes earlier, especially in cases of mild kidney damage where serum creatinine levels are not significantly elevated." (PMID 40551898, 2025). "We found that the nephropathy group exhibited the highest mean serum cystatin C level, which was higher (though not statistically significant) than that of the HC (p = 0.15), ALS (p = 0.15), Alzheimer’s (p = 0.15) and Parkinson’s (p = 0.31) groups." (PMID 41009467, 2025). "Notably, our investigation demonstrated that HMGB1 knockdown correlated with increased Cystatin C levels, typically indicative of low GFR and high kidney damage." (PMID 38187339, 2024).
kidney damage (continued). "In type 2 diabetes patients with nephropathy, we found significant lipoprotein abnormalities and an increase in serum cystatin C (P < 0.001) compared to those without nephropathy." (PMID 37082121, 2023). "Cystatin C, a sensitive serum marker of preclinical nephropathy, is not affected by muscle conditions and is more sensitive than creatinine." (PMID 35284141, 2022). "Markers of kidney damage, such as albuminuria and cystatin-C were not available in our data and missing data for some predictor variables precluded prognostic risk estimates for some models." (PMID 34997924, 2022). "If cisplatin had a significant effect on creatinine due to kidney damage, this would have been reflected in cystatin C levels, which was not the case." (PMID 33319340, 2021). "Biomarkers, such as cystatin C, are perceived to be better markers of kidney damage, but these are not yet commonly implemented in this specific clinical neonatal setting." (PMID 34200017, 2021). "Cystatin C is recommended as an interoceptive biomarker indicating kidney function when Cr levels are not yet affected, such as during the early stages of kidney damage and with mildly decreased GFR." (PMID 30145854, 2019). "In a 1-year follow-up of 112 hypertensive patients without known nephropathy, the baseline RRI ≥ 0.7 was associated with significant worsening of renal function measured by serum cystatin C concentration." (PMID 23959401, 2014). "It has been suggested that newer urinary biomarkers such as cystatin C, KIM-1 or NGAL may be more sensitive to identify kidney damage." (PMID 23383076, 2013). "The measurement of cystatin C in urine (UcysC) has been shown to be a suitable and non-invasive method to detect renal pathologies; increased UcysC concentrations allow for the accurate detection of tubular dysfunction among pure and mixed nephropathies." (PMID 38732023, 2024). "To elucidate whether short-term PM2.5 exposure could induce kidney damage, we exposed BALB/c mice to PM2.5 intratracheally and measured the biomarkers of kidney injury (KIM-1, cystatin C), oxidative stress (MDA, SOD-1, and HO-1), and inflammatory response (NF-κB, TNF-α)." (PMID 30151074, 2018). "However, the 2013 Kidney Disease Improving Global Outcomes (KDIGO) CKD Guideline Development Work Group suggests measuring cystatin C for confirmation of CKD only when markers of kidney damage are absent and eGFR by creatinine-based formulae is 45–59 mL/min per 1.73 m2." (PMID 32854641, 2020). "The study found significantly higher serum cystatin C levels and SBP and lipid profile abnormalities in type 2 diabetics with nephropathy compared to those without nephropathy." (PMID 37082121, 2023). "However, in the case of serum cystatin C levels, TC, and TG, this study agreed with the findings of the present study, and unlike our finding, it found a significant difference in serum creatinine in type 2 diabetics with nephropathy compared to those without nephropathy." (PMID 37082121, 2023). "We found that serum cystatin C is not significantly affected by sex, unlike serum creatinine, and a significant difference was found between T2DM patients with nephropathy and those without nephropathy." (PMID 37082121, 2023).
renal failure (80 papers, 2006 to 2026). "The association between cystatin C-based EKFC eGFR and kidney failure was stronger compared with cystatin C-based CKD-EPI2021 and CKD-EPI2012 eGFR." (PMID 41209168, 2025). "Some studies have demonstrated that lower levels of eGFR-cystatin C, relative to eGFR-creatinine, are associated with an increased risk of frailty, hospitalizations for heart failure, cardiovascular disease, kidney failure, and mortality." (PMID 40953152, 2025). "Multiple markers reflecting renal insufficiency were associated with increased dementia incidence, such as elevated cystatin C, creatinine and urea, as demonstrated in the U-shaped association." (PMID 35927253, 2022). "In patients with hepatorenal syndrome, cystatin C and urinary neutrophil gelatinase-associated lipocalin levels may contribute to diagnosis and treatment." (PMID 39336978, 2024). "Using a combination of the serum creatinine and cystatin C levels (eGFRscr_cys) could improve the bias (−0.3 for eGFRscr_cys) of the equation and achieve the highest diagnostic accuracy for renal insufficiency (AUC60, 0.953; P < 0.05, except for eGFR_MDRD)." (PMID 28693441, 2017). "Hence, individuals presenting with heightened levels of cystatin C may manifest early signs of renal insufficiency, thereby increasing their susceptibility to cardiovascular events." (PMID 39044229, 2024). "Serum creatinine and cystatin C directly reflect renal function, with the latter increasing during mild renal insufficiency, compensating for the delayed elevation of creatinine." (PMID 41169460, 2025). "Cystatin C-based GFR estimates have been shown to predict all-cause mortality, cardiovascular events, as well as kidney failure in diabetic and obese patients." (PMID 40004620, 2025). "Cystatin C (Cys-C), as a biomarker of early kidney failure, can be used to detect and prevent acute renal injury." (PMID 37367010, 2023). "Our study suggested that the level of cystatin C is also a strong predictive factor for kidney failure." (PMID 32524865, 2020). "The changes of cystatin C level in the peripartum period seem to exclude the possibility of using cystatin C as a marker for renal insufficiency but additional research is necessary for investigating the matter further." (PMID 26904684, 2016). "Cystatin C is considered to be a high-sensitivity marker of renal insufficiency and can also be useful in pregnancy complicated by gestational diabetes mellitus or preeclampsia." (PMID 26904684, 2016). "The insignificant changes of cystatin C level in the peripartum period seem to exclude the possibility of using cystatin C as a marker for renal insufficiency in the peripartum period but additional research is necessary to investigate the matter further." (PMID 26904684, 2016). "Cystatin C as a marker for renal failure has been shown to be of prognostic value; however, a wide range of its predictive accuracy has been reported." (PMID 24397879, 2014). "CKD-EPI equations based on cystatin C detect more MM patients with stages 3–5 kidney failure than equations based only on serum creatinine, namely, the MDRD and the original CKD-EPI equations." (PMID 24877060, 2014). "Concordant results were described for a population of patients treated in a general intensive care unit, with an increase of the number of cases identified as renal insufficiency when GFR estimation was made from serum cystatin C." (PMID 22746300, 2012). "These included proteins involved in atherosclerosis/inflammation (e.g. GDF-15, lipopolysaccharide binding protein, and CD14), extracellular matrix [matrix metalloproteinase-7 (MMP7)], heart failure [N-terminal pro-B-type natriuretic peptide (NT-proBNP)], and renal insufficiency cystatin C (CST3)." (PMID 39660078, 2024). "The impact of RAS inhibition on cystatin C levels may be a valuable research target with a potential benefit in delaying future kidney failure, which will need further dedicated studies to explore." (PMID 40034484, 2024).
renal failure (continued). "Cystatin C testing (eGFRcys or eGFRcr‐cys) can be used to: (i) improve specificity of diagnosis of CKD in older people; and (ii) stratify the risk of cardiovascular disease, kidney failure, and death in older patients." (PMID 36151987, 2022). "Compared with CKD-EPIscr and CKD-EPIcys, the use of the combination of serum creatinine and cystatin C (CKD-EPI scr_cys) levels could improve the bias of the equation and achieve a higher diagnostic accuracy for renal insufficiency." (PMID 28693441, 2017). "Cystatin C is a novel and more sensitive marker of early renal insufficiency." (PMID 26107522, 2015). "The higher plasma TMAO level was found to be predictive of poor long-term survival in patients without CKD (eGFR ≥ 60 ml/min) irrespective of cystatin C levels implying that increase in TMAO levels may occur before the renal insufficiency (i.e., rise in cystatin C)." (PMID 36310589, 2022). "In a healthy human, the concentration of Cystatin-C in whole blood is in the range of 0.51–1.5 μg/mL, which can increase up to ten times the normal levels as GFR decreases when kidney failure occurs." (PMID 38248407, 2024). "Compared with serum creatinine, cystatin C is more precise in detecting initial stages of CKD and in predicting adverse outcomes such as kidney failure, cardiovascular disease and mortality." (PMID 40034484, 2024). "Cystatin C has been shown to have greater accuracy than creatinine in detecting initial stages of CKD and predicting adverse outcomes such as kidney failure and cardiovascular disease." (PMID 40034484, 2024). "In this group of peritoneal dialysis patients, cystatin C did not correlate with the metabolic or inflammatory status, nor cardiovascular disease, after adjustment for residual renal function." (PMID 31799980, 2020). "Moreover, cystatin C-based GFR estimation may be better than using creatinine-based eGFR for this study because most subjects did not have severe renal insufficiency." (PMID 31557071, 2019). "In addition, exogenous APN supplementation may be superior to full-length APN in renal insufficiency because exogenous APN lacks the NH2-terminal structural domain and does not bind to and inactivate cystatin C." (PMID 38368320, 2024).